HDAC6 (histone deacetylase 6)
Diseases named in the same sentence as HDAC6 in open-access papers (continued):
Sharing a sentence is not in itself a finding about the gene and the disease.
thyroid cancer (5 papers, 2015 to 2023). "In thyroid cancer cells, HDAC6 potentiates RUNX2 transcription, stabilizing the assembly of the transcriptional complex on the RUNX2 P2 promoter." (PMID 36551878, 2022). "To further elucidate the functional interplay between RUNX2 and HDAC6, we sought to investigate the transcriptional program of the RUNX2- HDAC6 complex, in thyroid cancer cells." (PMID 31395086, 2019). "Since a functional interplay between RUNX2 and HDAC6 has been suggested, we used RNA-Seq profiling to consolidate this evidence in thyroid cancer and to extend the knowledge on this cooperation in a setting in which HDAC6 also controls RUNX2 expression." (PMID 31395086, 2019). "HDAC6, which represents the most thoroughly studied class II isoform, has been correlated with a higher tumor grade in salivary gland neoplasms, and advanced pathological stages in oral squamous cell and thyroid carcinomas." (PMID 36901692, 2023). "i) Correlation of RUNX2 and HDAC6 expression in thyroid cancer samples from TCGA database." (PMID 31395086, 2019). "Furthermore, we found an additional and cell-specific function of HDAC6 in driving RUNX2 expression in thyroid cancer cells." (PMID 31395086, 2019). "Thus, we explored whether HDAC6 assists RUNX2 in the regulation of specific target genes in thyroid cancer, beside their cooperation in controlling RUNX2 expression." (PMID 31395086, 2019). "Being tubacin a HDAC6 specific inhibitor, these data indicate that HDAC6 is selectively involved in RUNX2 transcription in this thyroid cancer cell line, highlighting a close connection between proliferation inhibition and RUNX2 down-regulation." (PMID 31395086, 2019).
asthma (4 papers, 2016 to 2021). "In the present study, we found that HDAC6 could relieve the airway inflammation, airway remodeling and airway hyperresponsiveness in asthma." (PMID 27565183, 2016). "In this context, a recent study demonstrated therapeutic effects of both HDAC6 and HDAC8 inhibitors in a mouse model of asthma." (PMID 30405614, 2018). "Tubastatin A (Tub-A), a highly selective histone deacetylase 6 (HDAC6) inhibitor, has been widely used as a cytotoxic anticancer agent, or for the treatment of patients with asthma." (PMID 28811599, 2017). "It is known that HDAC6 can promote CD8 T cell activation during allergic skin inflammation, mediate the activation of TGFβ-Notch signaling, and mediate airway hyperresponsiveness in obese mice with asthma." (PMID 34234781, 2021). "However, the role of HDAC6 in the treatment of asthma may not be realized by conventional anti-inflammatory effects but achieved by relieving the epithelial damage/repair and proliferation, differentiation and migration of the airway smooth muscle." (PMID 27565183, 2016).
autosomal dominant polycystic kidney disease (4 papers, 2018 to 2026). Autosomal dominant form of polycystic kidney disease. "Meanwhile, the elevated expression of histone deacetylase 6 (HDAC6) have been confirmed to be involved in renal diseases including AKI, autosomal dominant polycystic kidney disease, and hypertensive nephropathy for the contribution to inflammation, apoptosis and fibrosis." (PMID 31639165, 2019).
chondrosarcoma (4 papers, 2018 to 2023). A malignant cartilaginous matrix-producing mesenchymal neoplasm arising from the bone and soft tissue. "The inhibition of HDAC6 causes PC restoration and suppresses the proliferation and invasion of chondrosarcoma cells." (PMID 37510333, 2023). "Recently, histone deacetylase 6 (HDAC6) has been implicated in suppression of cilia formation in human chondrosarcoma." (PMID 29361725, 2018). "AURKA was found to be upregulated in non-ciliated ovarian and renal cell carcinoma cells, and HDAC6 inhibition restored PCs in chondrosarcoma and cholangiocarcinoma cancer cells, suppressing cell proliferation and invasion capacity." (PMID 37510333, 2023). "Additionally, HDAC6 inhibition also suppresses proliferation and invasion in chondrosarcoma tumor cells and restores the expression of PCs." (PMID 37510333, 2023). "Furthermore, the abnormal expression of HDAC6 and IFT88 has been described in chondrosarcoma tissues." (PMID 37510333, 2023).
COVID-19 (4 papers, 2022 to 2024). A disease caused by infection with severe acute respiratory syndrome coronavirus 2. "HDAC6 inhibition has the potential to be used to minimize the morbidity associated with severe COVID-19 via modulating the innate and adaptive immune systems." (PMID 37638049, 2023). "HDAC6-selective inhibition has been proposed as a therapeutic strategy to restore the immune response in severe COVID-19 patients." (PMID 38162580, 2023). "Overall, the data presented here support the notion of testing HDACi, and possibly HDAC6 selective inhibitors for severe COVID-19 treatment." (PMID 35592335, 2022). "In this regard, HDAC6 inhibitors were found to reduce cytokine release, decrease T cell exhaustion, and contribute to innate immune cell memory processes, potentially providing therapeutic benefits in severe COVID-19 cases." (PMID 38932355, 2024). "Moreover, since the inflammation in COVID-19 patients is partially driven by NF-κB and characterized by increased TNF-α and IL-6 production, we investigated the global effect of the HDAC6 inhibitor ITF3756 on purified human monocytes stimulated with TNF-α." (PMID 35592335, 2022). "HDAC6 inhibition, which blocks IFN-I synthesis and its downstream effects in airway epithelial cells and immune cells, may be able to mitigate the negative effects generated in severely ill COVID-19 patients by late or extended activation of the IFN-I pathway." (PMID 37638049, 2023).
cystic kidney disease (4 papers, 2018 to 2023). A congenital or acquired kidney disorder characterized by the presence of renal cysts. "Histone deacetylase 6 (HDAC6) has also been reported to be involved in renal cyst formation in mammals." (PMID 34545930, 2021). "For instance, Tubastatin A reduced renal enlargement in SNx rats, a finding aligned with a recent report of the anti-proliferative effects of HDAC6 inhibition in kidney cells and in cystic kidney disease." (PMID 29449811, 2018).
diabetic kidney disease (4 papers, 2020 to 2022). Progressive kidney disorder caused by vascular damage to the glomerular capillaries, in patients with diabetes mellitus. "In this research, we observed that HDAC6 was markedly activated in kidney of diabetic nephropathy patients, db/db mice and AGE‐treated podocytes." (PMID 32885602, 2020). "Previous studies have shown beneficial effects of HDAC6 inhibition in diabetic kidney disease and diabetic heart disease." (PMID 32660051, 2020). "While the specific role of HDAC6 in the diabetic retina has not been studied before, HDAC6 inhibition has been shown to alleviate myocardial ischemia-reperfusion injury in diabetic rats and to ameliorate diabetic kidney disease, predominantly through antioxidant effects." (PMID 32660051, 2020). "Based on the pathogenesis role of HDAC6 in various diseases, we hypothesized that HDAC6 acts as an important molecule in advanced glycation end products (AGE)‐induced podocyte damage and the development of diabetic nephropathy." (PMID 32885602, 2020).
inflammatory breast carcinoma (4 papers, 2017 to 2022). An advanced, invasive breast adenocarcinoma characterized by the presence of distinct changes in the overlying skin. "It is also important to show that HDAC6, far from being an essential gene in its entirety, could be an essential gene for some specific functions, as has been shown in inflammatory breast cancer." (PMID 34073238, 2021). "Another interesting function of HDAC6 is found in the inflammatory breast cancer (IBC) cells." (PMID 30176876, 2018). "Notably, HDAC6 activity is significantly increased in inflammatory breast cancer, even though HDAC6 is not overexpressed." (PMID 35159049, 2022).
oral cancer (4 papers, 2021 to 2024). "To analyze the effect of HDAC6 on cell growth in oral cancer cell lines, we evaluated cell growth with a CCK-8 assay in the OC-2 and OECM-1 cell lines." (PMID 35732647, 2022). "Among the rest of HDACs, studied in oral cancer, HDAC-6, HDAC-8 and HDAC-9 revealed to be upregulated in oral SCC, without demonstrating any interaction with clinicopathological parameters, other than tumor aggressiveness in the case of HDAC-6." (PMID 34441281, 2021).
Peritoneal Fibrosis (4 papers, 2017 to 2024). Disorder characterized by a wide range of structural changes in PERITONEUM, resulting from fibrogenic or inflammatory processes. "Recently we have demonstrated that HDAC6 is critically implicated in HG-PDF induced peritoneal fibrosis, and overexpressed in the peritoneum and dialysis effluent from PD patients." (PMID 35784347, 2022). "Overall, several clinical trials have proved the effectiveness, security, applicability of selected HDAC6 inhibitors in clinical treatment, which provides opinions and possibilities of the application of HDAC6 inhibitors in peritoneal fibrosis associated with peritoneal dialysis in the future." (PMID 35784347, 2022). "Selective inhibition of HDAC6 significantly reduces CG-induced peritoneal fibrosis progression by limiting EMT and extracellular matrix protein deposition." (PMID 39749340, 2024). "To better clarify the role of HDAC6 in peritoneal fibrosis, we established a murine peritoneal fibrosis model by intraperitoneally injecting 0.1% CG every other day for 21 days." (PMID 35784347, 2022). "In summary, the present study revealed the fibrogenic role of HDAC6 in CG-induced peritoneal fibrosis, and the anti-fibrotic effect of TA mediated by suppressing macrophage M2 polarization." (PMID 35784347, 2022). "Except for HDAC6, another subtype of HDAC family, HDAC1 from class I has also been confirmed to be associated with peritoneal fibrosis." (PMID 35784347, 2022). "Here, we focused on the role and mechanisms of HDAC6 in chlorhexidine gluconate (CG) induced peritoneal fibrosis and discussed the mechanisms involved." (PMID 35784347, 2022). "This study will further clarify the role and mechanism of HDAC6 in M2 macrophage polarization, and recommend HDAC6 as a potential target for therapy of peritoneal fibrosis in the future." (PMID 35784347, 2022). "In another word, the PI3K/AKT pathway mediated by HDAC6 was involved in the regulation of M2 polarization in peritoneal fibrosis." (PMID 35784347, 2022). "We found Tubastatin A (TA), a selective inhibitor of HDAC6, significantly prevented the progression of peritoneal fibrosis, as characterized by reduction of epithelial-mesenchymal transition (EMT) and extracellular matrix (ECM) protein deposition." (PMID 35784347, 2022). "In this study, we explored the role of HDAC6 in M2 macrophage polarization in a chlorhexidine gluconate (CG)-induced peritoneal fibrosis model by using a selective HDAC6 inhibitor Tubastatin A (TA)." (PMID 35784347, 2022). "To confirm the therapeutic effect of HDAC6 inhibition, we treated the CG-induced peritoneal fibrosis mouse model with TA and found a significant alleviation of fibrosis and reduced extracellular matrix protein deposition." (PMID 35784347, 2022). "Our studies suggest that TA, a special inhibitor of HDAC6, can alleviate the development and progression of peritoneal fibrosis, which provides a rationale for using HDAC6-specific inhibitors as potential anti-fibrotic drugs in clinical trials." (PMID 29179471, 2017). "In conclusion, we demonstrated for the first time that the inhibition of HDAC6 is successful in preventing the development of peritoneal fibrosis." (PMID 29179471, 2017). "Our data suggest that HDAC6 inhibition prevents peritoneal fibrosis by blocking the TGF-β1/Smad signaling pathway." (PMID 29179471, 2017). "Collectively, these results suggest that HDAC6 inhibition can attenuate peritoneal fibrosis by inhibiting multiple pro-fibrotic signaling pathways, EMT, inflammation and blood vessel formation." (PMID 29179471, 2017). "Administration of TA at 70 mg/kg every day immediately after injection of high glucose dialysate significantly reduced these pathological changes, suggesting that HDAC6 is a critical mediator of peritoneal fibrosis." (PMID 29179471, 2017). "Collectively, these results illustrate that HDAC6 is involved in the development of peritoneal fibrosis." (PMID 29179471, 2017).
Peritoneal Fibrosis (continued). "To summarize, blocking HDAC6 with TA may ameliorate CG-induced peritoneal fibrosis progression by abolishing M2 macrophage polarization." (PMID 39749340, 2024). "Our results support that the HDAC6 could enhance M2 polarization to promote peritoneal fibrosis via regulating the TGF-β/Smad3 signaling." (PMID 35784347, 2022). "All the data showed us that HDAC6 overexpressed in the CG-induced peritoneal fibrosis and the degree of peritoneal fibrosis injury could be ameliorated by inhibition of HDAC6." (PMID 35784347, 2022). "Collectively, our study revealed that blockade of HDAC6 by TA could suppress the progression of CG-induced peritoneal fibrosis by blockade of M2 macrophage polarization." (PMID 35784347, 2022). "In addition to its involvement in tumor proliferation, invasion and metastasis, HDAC6 also plays an important role in cardiac fibrosis, renal fibrosis, peritoneal fibrosis and many other fibrotic diseases." (PMID 35784347, 2022). "In this study, we further proved that HDAC6 could aggravate CG-induced peritoneal fibrosis via promoting macrophage polarization to the M2 phenotype." (PMID 35784347, 2022). "Therefore, this study clarified the importance of HDAC6 in peritoneal fibrosis from a new mechanism point that HDAC6 contributed to M2 macrophage polarization." (PMID 35784347, 2022). "HDAC6 could be a potential therapeutic target for the prevention and treatment of peritoneal fibrosis." (PMID 34526901, 2021). "Our results suggest that a clinical trial aimed at preventing and/or treating peritoneal fibrosis by using HDAC6 inhibitors might be possible." (PMID 29179471, 2017). "Taken together, these results indicate that HDAC6 activity is required for the activation of NF-κB signaling pathways and for the production and release of multiple inflammatory cytokines and chemokines in peritoneal fibrosis." (PMID 29179471, 2017). "Although our understanding of the mechanism of HDAC6 mediated peritoneal fibrosis remains incomplete, our results suggest that HDAC6 activation is critically involved in the EMT of peritoneal mesothelial cells and differentiation of fibroblasts into myofibroblasts." (PMID 29179471, 2017). "HDAC6 inhibition-elicited suppression of inflammation may also contribute to attenuation of peritoneal fibrosis." (PMID 29179471, 2017). "Therefore, targeting HDAC6 holds promise for treating peritoneal fibrosis." (PMID 39749340, 2024). "In addition, the staining colocalized HDAC6 and Arginase-1 in IL-4-stimulated Raw264.7 cells, which provided support that HDAC6 might promote peritoneal fibrosis via manipulating M2 polarization." (PMID 35784347, 2022). "Taken together, these results suggested that M2 macrophage polarization was involved in the process of peritoneal fibrosis, and inhibition of HDAC6 by TA could not only prevent the macrophage infiltration but also M2 polarization, resulting in amelioration of peritoneal fibrosis." (PMID 35784347, 2022). "HDAC6 inhibition may also attenuate peritoneal fibrosis via the targeting of EGFR signaling." (PMID 29179471, 2017). "The role of histone deacetylase 6 (HDAC6) in peritoneal fibrosis remains unknown." (PMID 29179471, 2017). "As a first step toward understanding whether HDAC6 is involved in the regulation of peritoneal fibrosis, we examined the effect of TA, a highly selective inhibitor of HDAC6, on the EMT ofcultured human peritoneal mesothelial cells (HPMCs) in response to TGF-β1." (PMID 29179471, 2017). "Currently, the role of HDAC6 in peritoneal fibrosis remains unknown." (PMID 29179471, 2017). "Thus, HDAC6 may be a promising target in peritoneal fibrosis treatment." (PMID 35784347, 2022). "In an animal model of peritoneal fibrosis induced by high glucose dialysate, we found that α-SMA is co-localized with HDAC6 in the cells in the submesothelial interstitium and administration of TA largely blocked expression of α-SMA." (PMID 29179471, 2017).
Peritoneal Fibrosis (continued). "Our results reveal a critical role of HDAC6 in mediating the EMT of mesothelial cells, activation of submesothelial fibroblasts and development of peritoneal fibrosis." (PMID 29179471, 2017). "In this study, we examined the effect of HDAC6 inhibition on the epithelial–mesenchymal transition (EMT) of peritoneal mesothelial cells and development of peritoneal fibrosis." (PMID 29179471, 2017). "Thus, HDAC6 may represent a viable target for the prevention and treatment of peritoneal fibrosis." (PMID 29179471, 2017). "Recently we have demonstrated that histone deacetylase 6 (HDAC6) is critically implicated in high glucose peritoneal dialysis fluid (HG-PDF) induced peritoneal fibrosis, however, the precise mechanisms of HDAC6 in peritoneal fibrosis have not been elucidated." (PMID 35784347, 2022). "However, the precise mechanisms of HDAC6 in peritoneal fibrosis have not been elucidated." (PMID 35784347, 2022). "However, the role of HDAC6 in peritoneal fibrosis has not yet been reported." (PMID 29179471, 2017). "Since HDAC6 KO mice do not show abnormal function of major organs, there may promise in developing HDAC6 inhibitors as drugs for use in the prevention and/or treatment of chronic complications like peritoneal fibrosis." (PMID 29179471, 2017).
renal carcinoma (4 papers, 2020 to 2024). A carcinoma arising from the epithelium of the renal parenchyma or the renal pelvis. "HDAC6 was detected in the cytoplasm of renal cancer cells, of which approximately 40% showed high expression and approximately 60% showed low expression." (PMID 39063958, 2024). "We confirmed that HDAC6 was expressed in renal cancer cell lines using Western blot and immunohistochemistry." (PMID 39063958, 2024). "In this study, we elucidate the anticancer properties of selective HDAC6 inhibitors in renal cancer cell lines, shedding light on their potential therapeutic efficacy and paving the way for further exploration into their clinical application." (PMID 39063958, 2024). "The overexpression of HDAC1 and its contribution to tumorigenesis has been found in various tumors, such as gastric, prostate, liver, breast (as well as HDAC6 and HDAC8), colorectal and renal carcinoma (alongside with HDAC6)." (PMID 38004560, 2023). "Furthermore, inhibition of HDAC6 in Vhl–/– human renal carcinoma cells led to reduced HIF-1α expression and activity." (PMID 32984302, 2020). "To evaluate whether HDAC6 expressed in the kidney of IgAN, we collected renal biopsy specimens from IgAN patients and specimens of normal renal cortex tissue that was not affected by the tumor from patients with renal carcinoma." (PMID 33896334, 2021).
renal cell carcinoma (4 papers, 2021 to 2025). "It is reported that high HDAC6 expression was an independent, poor prognostic factor in renal cell carcinoma (RCC) patients, and HDAC6 are considered to be a biomarker of RCCs prognostic and an indicator for RCC progression." (PMID 33896334, 2021).